KLHDC7A (kelch domain containing 7A)
Synonyms: FLJ38753
Tractability: Antibody: UniProt predicts a signal peptide or a membrane-spanning region. PROTAC: its protein half-life has been measured.
Gene: Protein-coding gene on chromosome 1 (18,480,930 to 18,485,974, forward strand). Ensembl gene ENSG00000179023.
Subcellular location: Membrane
Subcellular location (Human Protein Atlas): Nuclear speckles
Gene Ontology:
Molecular function: protein binding
Cellular component: membrane
Genetic constraint (gnomAD): Loss-of-function variants: 0 observed, 0.46 expected, observed/expected ratio (o/e) 0, 90% interval 0 to 1.84. That is too few expected variants to judge how well the gene tolerates losing a copy. Missense variants: 1,123 observed, 1,064.6 expected, observed/expected ratio (o/e) 1.05, 90% interval 1 to 1.11. Synonymous variants: 464 observed, 466.81 expected, observed/expected ratio (o/e) 0.99, 90% interval 0.92 to 1.07.
Homologues: Orthologues: chimpanzee KLHDC7A (97% identical), macaque KLHDC7A (90% identical), pig KLHDC7A (74% identical), rat Klhdc7a (70% identical), dog KLHDC7A (70% identical), mouse Klhdc7a (69% identical), tropical clawed frog KLHDC7A (38% identical), zebrafish klhdc7a (33% identical). Paralogues in human: KLHDC7B (27% identical), KBTBD11 (25% identical), KLHL42 (14% identical), KLHL1 (14% identical), KLHL4 (14% identical), KLHL5 (14% identical), KLHL35 (14% identical), KLHL13 (13% identical), KLHL20 (13% identical), KLHL9 (13% identical), KLHL24 (13% identical), KLHL17 (13% identical), and 42 more.
Diseases named in the same sentence as KLHDC7A in open-access papers:
KLHDC7A is named in the same sentence as 2 diseases in open-access papers, as found by Europe PMC text mining. Sharing a sentence is not in itself a finding about the gene and the disease. The quoted sentences say what the papers report.
cancer (1 paper, 2023). A tumor composed of atypical neoplastic, often pleomorphic cells that invade other tissues. "In patients with cancer of the bones, joints, the articular cartilage of limbs, lower expression of KLHDC7A, whose expression was also lower in Xenopus tumors, had decreased survival rates." (PMID 37580380, 2023).
KLHDC7A also shares sentences with these, for which no sentence is quoted: diabetic retinopathy (1 paper).